STAT3 (signal transducer and activator of transcription 3)
Diseases named in the same sentence as STAT3 in open-access papers (continued):
Sharing a sentence is not in itself a finding about the gene and the disease.
tumor (continued). "While TAMs are observed in primary tumors of children with high-risk disease, the mechanism of their contribution to tumor growth and the relative role of IL-6 in STAT3 activation are not clearly understood." (PMID 29207662, 2017). "All three have been implicated in tumor proliferation, angiogenesis, and metastasis via activation of multiple upstream pathways, including STAT3, CXCR1 and CXCR2, and NF-κB, respectively." (PMID 27525640, 2017). "Taken together, these results indicate that the tumour environment manipulates DC functional deficiency by simultaneously attenuating canonical NF-κB and STAT3 signalling, leading to the abnormal transcription of downstream genes." (PMID 28350008, 2017). "STAT3 is a transcription factor for multiple genes associated with inflammation and tumor progression, but it is also an important transcription factor for micro RNAs (miRNAs)." (PMID 29333002, 2017). "Stat3 depletion and inhibition in cancer cell lines and in tumours in vivo caused significant inhibition of centrosome clustering and viability." (PMID 28474672, 2017). "Tumour-associated myeloid cell production of IL-6 promotes colon tumour cell proliferation and protection from apoptosis through activation of STAT3." (PMID 28210073, 2017). "The abnormal activation of STAT3 can cause unrestricted cell proliferation, malignant transformation and tumor angiogenesis." (PMID 28764703, 2017). "This strategy successfully identified 20 putative tumor-associated candidate genes in TAFs; some were previously reported as tumor-associated in TAFs, such as Stat3, Stab1, and Nfkbib." (PMID 29228606, 2017). "WP1066, a small-molecule, directly process of tumorgenesis and metastasis by inhibiting the phosphorylation of JAK2/STAT3 pathway and the subsequent downstream protein, such as survivin and c-Myc, which are associated with tumor formation." (PMID 28570563, 2017). "Various studies have shown that hyperactivation of Stat3 is implicated in tumor progression and treatment resistance and Stat3 blockade enhances the efficacy of chemotherapeutic agents in OSCC." (PMID 29050290, 2017). "The tumor promoting effect of IL-6 is mainly exerted by activation of the oncogenic transcription factors STAT3 and NF-κB, whereas loss of SOCS3 is important for further CAC progression." (PMID 28881611, 2017). "STAT3 and NF-κB that are constitutively activated by acetylation and/or phosphorylation in tumor cells, have been closely linked to both cancer development and progression." (PMID 29194365, 2017). "Now we demonstrate that loss of Hdac7 resulted in significantly enhanced Stat3 acetylation in both mouse primary tumors and human tumor cell lines." (PMID 29126425, 2017). "S1PR1 in tumor cells was previously shown to be linked to STAT3 activation, which contributed to stimulated IL-6 production." (PMID 28771545, 2017). "Activation of Stat3 regulates the expression of numerous genes associated with tumor invasion, metastasis and survival." (PMID 28360411, 2017). "Permanent loss of stem cell characteristics was observed when Stat3 is blocked and treatment with Stat3 inhibitor impressively inhibits tumor formation." (PMID 28927416, 2017). "It is well documented that STAT3 is phosphorylated for tumor progression and inflammation by receptor-associated Janus kinases (JAK)." (PMID 29254203, 2017). "Several reports suggested that PDIA3/ERp57 is associated with tumor progression and the modulation of STAT3 activity." (PMID 28489571, 2017). "TAMs from the same study showed downregulation of STAT3 phosphorylation, a mechanism that has been implicated in the shift of macrophage polarization from M2 to M1 in order to inhibit tumor growth and metastasis." (PMID 28970834, 2017). "Dysregulation of STAT3 has been associated with increased tumor cell proliferation, survival, invasion and immunosuppression in vitro, and mounting evidence supports the critical role of STAT3 as an oncogene." (PMID 28750090, 2017).
tumor (continued). "Several molecular signaling pathways within the myocyte have been implicated in driving tumor-induced muscle wasting, including forkhead boxO (FoxO), signal transducer and activator of transcription 3 (STAT3), and myostatin-activin receptor 2B." (PMID 27901481, 2017). "There is also compelling evidence that increased levels of apoptotic cells have been frequently observed in Stat3 inactive or deficient tumor cells." (PMID 29133922, 2017). "Expression of miR-135a, a tumor suppressor associated with STAT3, was inhibited by a high glucose environment." (PMID 28114390, 2017). "On the other hand, activated STAT3 negatively regulated LPS signaling and was associated with defective DC differentiation mediated by tumor cells or tumor-derived factors." (PMID 28099147, 2017). "The pathways and soluble factors activated in tumor-associated NK cells, cancer cells, and regulatory myeloid cells, which determine the outcome of cancer immunity, are all critically regulated by STAT3." (PMID 27148255, 2016). "In univariate analysis, both high ph-STAT1 (P=0.002) and ph-STAT3 (P<0.001) tumour cell expression were associated with improved CSS." (PMID 27769057, 2016). "A prior study demonstrated that MRP1 is activated by STAT3 and is associated with cisplatin resistance in atypical teratoid/rhabdoid tumor cells." (PMID 26799670, 2016). "These divergences suggest that further study is needed to shed more light on the underling mechanism of STAT3 signal pathway in pro-tumor microenvironment in different tumor types." (PMID 26959884, 2016). "This confirmed our major conclusion, low STAT1/high STAT3 expression is associated with increased tumor growth." (PMID 27191495, 2016). "Growing evidence has shown that blockade of constitutively activated STAT3 can cause apoptosis and decrease proliferation and cell migration in vitro, inhibit tumor growth in vivo, as well as enhance the sensitivity to chemotherapy and radiotherapy." (PMID 26883202, 2016). "In contrast, JAK2 deficiency delays tumour formation in GHtg mice, which is linked to insignificant oncogenic STAT3 signalling and reduced ROS-induced oxidative damage." (PMID 27713471, 2016). "High ph-STAT1 and ph-STAT3 tumour cell expression were also significantly associated with reduced tumour recurrence (P=0.003 and P=0.001 respectively)." (PMID 27769057, 2016). "Peripheral and tumor-associated NK cells from STAT3-targeted tumor-bearing mice also expressed elevated levels of NK activation markers NKG2D, CD69, and Fas ligand (FasL)." (PMID 27148255, 2016). "In contrast, high ph-STAT3 tumour cell expression was associated with down-regulation of the local inflammatory infiltrate as evidenced by decrease in the CD4+ T-lymphocytes." (PMID 27769057, 2016). "High ph-STAT3 tumour cell expression was negatively associated with tumour necrosis (P=0.001) and cellular inflammatory infiltrate as measured using CD4+ helper T-lymphocytes (P=0.024)." (PMID 27769057, 2016). "STAT3 signaling, an important inflammation-associated pathway in malignancies, has been recognized as a key therapeutic target to reduce tumor growth and metastasis." (PMID 26762586, 2016). "In the nucleus, STAT3 activates the transcription of genes associated with tumor metastasis, as well as the transcription of anti-apoptotic and angiogenic genes, similarly to its function in various types of cancer." (PMID 27462789, 2016). "Over the last years, accumulating evidences have demonstrated that S1P signaling was crucial for persistent activation of STAT3 in epithelial/tumor cells in inflammation-associated colon cancer." (PMID 27800303, 2016). "CTLA4 aptamer-STAT3 siRNA inhibits tumor-associated Tregs and reduces tumor burden in multiple mouse tumor models." (PMID 27456457, 2016). "In line with the changes in STAT1 levels, STAT3 knockdown in HCT116 and SW620 (low STAT1+low STAT3) caused a faster xenograft tumor growth." (PMID 27191495, 2016).
tumor (continued). "STAT3 regulation of inflammation during M. tuberculosis infection differs from tumor-associated inflammation by downregulating Foxp3+ Treg cells and macrophage inflammatory response and modulating Th cell response." (PMID 29051427, 2016). "It is also well known that NF-κB and Stat3 pathways govern cytokine productions in response to different stimuli, are associated with drug resistance, and regulate tumor angiogenesis and invasiveness." (PMID 26506421, 2016). "Further, increased activation of STAT3 and its target genes, such as survivin, is often associated with tumor resistance to chemotherapy and radiotherapy in the brain, breast, colon, rectum, head, neck, and lung." (PMID 26755645, 2016). "The combined analysis of 54 studies showed that STAT3 overexpression in tumor tissue was associated with worse 3-year OS of solid tumors (OR = 2.06, 95% CI = 1.57 to 2.71, P < 0.00001)." (PMID 26959884, 2016). "For example, STAT3 activation initiated by IL-6 in tumor-associated endothelial cells, TAM, and MSCs induces their ability to express VEGF and bFGF in a feed-forward loop that positively regulates angiogenesis within tumor tissues." (PMID 27756885, 2016). "High ph-STAT1 and ph-STAT3 tumour cell expression were associated with increased ER (both P≤0.001) and PR (both P <0.05), reduced tumour grade (P=0.015 and P<0.001 respectively) and necrosis (both P=0.001)." (PMID 27769057, 2016). "Unlike other STAT members, the loss of STAT3 function results in early embryonic lethality STAT3 and the suppression of tumour cell proliferation, suggesting its crucial role as an oncogenic factor." (PMID 27769057, 2016). "In comparison to control MMTV-Myc mice, loss of Stat3 increased the formation of hyperplastic areas in the mammary glands, accelerated tumorigenesis, and slowed tumor growth." (PMID 27589562, 2016). "STAT3 regulates tumor-associated inflammation, and its activation downregulates the Th1 response by upregulating Foxp3+ Treg cells." (PMID 29051427, 2016). "Although some of the cells expressing Stat3 exhibited morphology consistent with stromal cells or tumour-associated immune cells, others were consistent with neoplastic cells." (PMID 27711075, 2016). "It has been known for some time that constitutive STAT3 activation in tumor cells can regulate their susceptibility to NK-mediated cytolysis and the infiltration and migration of NK cells within the tumor microenvironment." (PMID 27148255, 2016). "In conclusion, the present study is the first to report that RT inhibits IL-12 through the IL-6/STAT3 signaling pathway in tumors and tumor-associated DCs." (PMID 26745884, 2016). "High levels of STAT3 phosphorylation in the tumor stroma often correlate with loss of intact tumor immune surveillance." (PMID 28149296, 2016). "Constitutive activation of STAT3 has been observed in various tumor cell lines and STAT3 activation is associated with cell survival and induction of growth signaling pathways." (PMID 27344974, 2016). "High ph-STAT3 tumour cell expression was positively associated with ER status (P<0.001), PR status (P=0.015) and negatively with increased tumour grade (P<0.001)." (PMID 27769057, 2016). "High ph-STAT3 tumour cell expression was associated with improved CSS compared to patients with low tumour cell expression (P<0.001)." (PMID 27769057, 2016). "Together, these results indicate that loss of Stat3 resulted in significant histological alterations to the Myc induced tumors in addition to the acceleration of tumor initiation and decreased tumor growth rate." (PMID 27589562, 2016). "STAT3 inhibition offers a potential strategy to downstream immunosuppressive effects of tumor-associated microglia." (PMID 27294132, 2016). "Immunohistochemistry (IHC) analysis confirmed loss of pY-Stat3 and Stat3 in Ptenpc−/−Stat3pc−/− tumour cells, while still being present in stromal cells." (PMID 26198641, 2015).
tumor (continued). "It provides a mechanistic explanation for the prognostic studies that have directly linked Oct4/Nanog, Stat3 signaling, and Snail with tumor recurrence, tumor metastasis, and poor survival in HCC patients." (PMID 25879771, 2015). "STAT3 is associated with human malignancies, oncogenic transformation, angiogenesis, and invasion by tumor metastases." (PMID 26580615, 2015). "Stat3 activation in tumor cells is associated with cell proliferation, cell survival, invasion, angiogenesis, and metastasis." (PMID 26169986, 2015). "Granulocyte–macrophage colony-stimulating factor and IL-6 expression were upregulated in Stat3-deficient tumours only at the latest time point." (PMID 25734337, 2015). "STAT3 would appear to be the most obvious choice of drug target, given that STAT3 signaling can have a profound influence on the immunosuppressive function of tumor-associated macrophages." (PMID 26343197, 2015). "STAT3/HIF-1α axis has been implicated in a number of cellular functions including tumor growth and metastasis." (PMID 26370982, 2015). "We also analyzed expression of STAT3, which has been linked to enhanced levels of tumor-associated macrophages, myeloid-derived suppressor cells, and poor T cell responses." (PMID 25949894, 2015). "Lastly, STAT3 phosphorylation was found in HNSCC tumor samples and has been associated with a poor prognosis." (PMID 26272737, 2015). "Numerous studies indicated that alternation of p-STAT3 expression in tumor samples was associated with prognosis of various human malignancies such as breast cancer, lung cancer, lymphoma." (PMID 26024373, 2015). "In accordance, loss of STAT3 and p14ARF expression in patient tumours correlates with increased risk of disease recurrence and metastatic PCa." (PMID 26198641, 2015). "Of note, Ptenpc−/−Stat3−/− tumours lacked p21 expression, displayed reduced numbers of PML nuclear bodies and decreased SA-β-Gal activity compared with Ptenpc−/− tumours, suggesting Stat3 as a novel mediator of senescence in response to loss of Pten." (PMID 26198641, 2015). "Treating Stat3-deficient mice at tumour initiation resulted in a reduction of tumour growth as well as a decrease in vascularization compared with vehicle-treated control mice." (PMID 25734337, 2015). "Conversely, the STAT3-shRNA attenuated the increased tumor angiogenesis caused by the miR-874-inhibitor." (PMID 25596740, 2015). "The PTPRD S1845fs*2 mutation detected in Patient #1′s tumor is an altered tumor suppressor gene that dephosphorylates the oncoprotein Stat3, thus inactivating it." (PMID 26510912, 2015). "Since PTEN is mutated or lost in only a minor fraction of primary PCa, other aberrations must occur (oncogene induction or loss of tumour suppressor function) to activate STAT3 and ARF to induce senescence in human cancers." (PMID 26198641, 2015). "Membrane-associated Hsp70 from tumor-derived exosomes has been shown to activate MDSC through STAT3 pathways." (PMID 26556857, 2015). "STAT3 plays a crucial role in prostate carcinogenesis, as sustained by the evidence that STAT3 knockdown is associated with inhibited tumor growth in preclinical models." (PMID 28031890, 2015). "More interestingly, reduced tumor growth by STAT3 signaling blockade was coupled with remarkable inhibition of cancer stem cells implicated by tumor sphere and CSCs self-renewal markers." (PMID 26556875, 2015). "WP1066 inhibited Stat3 activation in tumor-associated endothelial cells, reducing their infiltration and angiogenesis." (PMID 25881542, 2015). "STAT3 phosphorylation has been closely associated with transformation and proliferation of tumor cells." (PMID 25788267, 2015). "Detailed histopathological analysis revealed that Stat3-deficient murine tumours were better vascularized at all investigated time points, which was corroborated by increased CD31+ and von Willebrand Factor staining of vessel walls." (PMID 25734337, 2015).
tumor (continued). "In fact, STAT3 is constitutively activated in 35–60% of BrCs, and elevated levels of phosphorylated STAT3 are associated with apoptosis resistance, cell cycle progression, and tumor angiogenesis in invasive BrC tissues." (PMID 26360780, 2015). "Without observable heterogeneity, pooled estimates of 12 cohorts discovered that elevated p-STAT3 expression was significantly associated with poor tumor differentiation (OR = 1.895, 95% CI: 1.364–2.632, P<0.001, I2 = 0, Ph = 0.526)." (PMID 26024373, 2015). "Several reports have suggested that ERp57 is associated with tumor progression and modulation of STAT3 activity, although their findings are controversial." (PMID 25605256, 2015). "Overall, this is the first study, which demonstrates that N225K and A550V PTPN6 mutations cause loss-of-function leading to JAK3 mediated deregulation of STAT3 pathway and uncovers a mechanism that tumor cells can use to control PTPN6 substrate specificity." (PMID 26565811, 2015). "Upregulated phosphorylation of Stat3 is closely associated with the promotion of growth and inhibition of apoptosis in tumor cells." (PMID 24348829, 2014). "Recently estrogen has been proven to exert protective effects against HCC through IL-6 restrictions, STAT3 inactivation and tumour-associated macrophage inhibition." (PMID 24708807, 2014). "STAT3 is constitutively activated in most tumor cells and persistent STAT3 activation has been associated with both chemoresistance and radioresistance." (PMID 24722287, 2014). "Numerous reports have taken STAT3 as a critical link between tumor cells and their microenvironments by regulating tumor growth and tumor-associated inflammation." (PMID 25126546, 2014). "The increased tumor size upon loss of STAT3 was accompanied by reduced NK cell infiltration and decreased levels of the cytokine IFN-γ and the chemokine RANTES." (PMID 24473086, 2014). "Identifying agents that inhibit STAT-3, a cytosolic transcription factor involved in the activation of various genes implicated in tumour progression is a promising strategy for cancer chemoprevention." (PMID 25296162, 2014). "In the present study, STAT3 expression in tumor associated-B cells was found to be significantly inhibited by JSI124." (PMID 25013518, 2014). "Stat3 has been shown to maintain constitutive NF-κb activation in tumor-associated myeloid cells, and several inflammatory factors encoded by NF-κb target genes, notably IL-6 released by TAMs, are important Stat3 activators." (PMID 24723924, 2014). "Stat3, a key downstream target of IL-6 signaling, promotes the expression of several genes that are associated with cell survival, leading to tumor cell proliferation, apoptosis inhibition and an increased metastatic potential." (PMID 24348829, 2014). "Intriguingly, we found that STAT3-deficient tumors were substantially larger, which was accompanied by reduced NK cell recruitment to the tumor." (PMID 24473086, 2014). "Consistent with this, STAT3 has been shown to be important in the regulation of the multi-directional feed-forward loop between tumor-associated myeloid cells, endothelial cells and tumor cells in tumor angiogenesis." (PMID 25013518, 2014). "Constitutive STAT3 activation has been implicated in the suppression of host antitumor immune response, thereby facilitating unregulated tumor growth." (PMID 24518612, 2014). "Evasion of anti-tumor immunity: The concept that STAT3 has a role in dampening the anti-tumor immune response came from the observation that tumor cell death induced by STAT3 blockade is associated with infiltration of various immune effector cells." (PMID 24995504, 2014).